PLEKHH2 (pleckstrin homology, MyTH4 and FERM domain containing H2)
Description:
In the kidney glomerulus may play a role in linking podocyte foot processes to the glomerular basement membrane. May be involved in stabilization of F-actin by attenuating its depolymerization. Can recruit TGFB1I1 from focal adhesions to podocyte lamellipodia.
Synonyms: KIAA2028; PLEKHH1L
Tractability: Antibody: UniProt places it where antibodies can reach, with high confidence; its Gene Ontology location is reachable by antibodies, with high confidence; the Human Protein Atlas places it where antibodies can reach.
Safety:
Unwanted effects reported when the protein is acted on. In parentheses: how it was acted on, where the effect was seen, and who reports it.
diabetes (source: ClinPGx)
Gene: Protein-coding gene on chromosome 2 (43,637,260 to 43,767,987, forward strand). Ensembl gene ENSG00000152527.
Subcellular location: Cytoplasm; Cytoplasm, cytoskeleton; Cell membrane; Cell projection, lamellipodium
Subcellular location (Human Protein Atlas): Cytosol; Plasma membrane; Nuclear bodies; Nucleoplasm
Gene Ontology:
Molecular function: protein binding; actin binding
Biological process: negative regulation of actin filament depolymerization
Cellular component: cytoplasm; lamellipodium; plasma membrane; cortical actin cytoskeleton; cell periphery; cytoskeleton
Genetic constraint (gnomAD): Loss-of-function variants: 100 observed, 144.26 expected, observed/expected ratio (o/e) 0.69, 90% interval 0.59 to 0.82. The upper end of that interval is the gene's LOEUF score, 0.82, which puts it in group 3 of 6, group 1 being the genes least tolerant of losing a copy. Missense variants: 1,766 observed, 1,550.3 expected, observed/expected ratio (o/e) 1.14, 90% interval 1.1 to 1.18. Synonymous variants: 606 observed, 551.3 expected, observed/expected ratio (o/e) 1.1, 90% interval 1.03 to 1.18.
Homologues: Orthologues: macaque PLEKHH2 (98% identical), chimpanzee PLEKHH2 (97% identical), pig PLEKHH2 (95% identical), dog PLEKHH2 (95% identical), rabbit PLEKHH2 (95% identical), guinea pig PLEKHH2 (86% identical), mouse Plekhh2 (86% identical), rat Plekhh2 (85% identical), tropical clawed frog plekhh2 (69% identical), zebrafish plekhh2 (54% identical), Drosophila melanogaster CG43867 (37% identical), Caenorhabditis elegans max-1 (21% identical). Paralogues in human: PLEKHH1 (47% identical).
Diseases named in the same sentence as PLEKHH2 in open-access papers:
PLEKHH2 is named in the same sentence as 15 diseases in open-access papers, as found by Europe PMC text mining. Sharing a sentence is not in itself a finding about the gene and the disease. The quoted sentences say what the papers report.
lung carcinoma (2 papers, 2022 to 2023). "After transfection with PLEKHH2-siRNAs in lung cell lines, we observed that PLEKHH2 silencing inhibited the proliferation, migration, and invasion of lung cancer cells and reduced the expression of proliferation-associated and invasion-associated proteins." (PMID 36209201, 2022). "Immunofluorescence and co-immunoprecipitation analyses were performed to elucidate the molecular mechanism underlying PLEKHH2-mediated regulation of proliferation and invasion in lung cancer cells." (PMID 36209201, 2022). "In this study, we explored the role of PLEKHH2 and the possible mechanisms by which it promotes the proliferation and invasion of lung cancer cells, mediated by its FERM domain." (PMID 36209201, 2022). "Further experiments showed that increased PLEKHH2 expression increased the migration and invasion ability of lung cancer cells." (PMID 36209201, 2022). "In the present study, we demonstrated that PLEKHH2 plays a vital role in promoting the malignant phenotype of lung cancer." (PMID 36209201, 2022). "The results showed that PLEKHH2 upregulation promoted FAK phosphorylation in lung cancer cell lines." (PMID 36209201, 2022). "We observed that increased expression of PLEKHH2 increased the number of colonies and the size of lung cancer cells and accelerated cell growth." (PMID 36209201, 2022). "Western blot analysis, and immunofluorescence were then performed in lung cancer cell lines, which showed increased PLEKHH2 expression compared to that in HBE cells." (PMID 36209201, 2022). "In 143 of 197 lung cancer specimens (72.59%), PLEKHH2 showed increased cytoplasmic expression." (PMID 36209201, 2022). "Hence, it would be interesting to explore the role and possible molecular mechanisms of PLEKHH2 in regulating the occurrence and development of lung cancer." (PMID 36209201, 2022). "Therefore, we established that PLEKHH2 promotes the malignant phenotype of lung cancer cells by activating the PI3K/AKT signaling pathway." (PMID 36209201, 2022). "Whether β-arrestins and FAK are involved in PLEKHH2-mediated regulation of the PI3K/AKT or Ras/ERK signaling pathways in lung cancer is an open question." (PMID 36209201, 2022). "In summary, this study aimed to explore the expression pattern of PLEKHH2 in NSCLC and its possible regulatory mechanism, providing new insights into the molecular mechanisms of lung cancer recurrence and metastasis." (PMID 36209201, 2022). "Here, we aimed to clarify whether PLEKHH2 has a regulatory effect on both the PI3K/AKT and Ras/ERK signaling pathways in lung cancer." (PMID 36209201, 2022). "The role of PLEKHH2 in regulating the PI3K/AKT or Ras/ERK signaling pathways in lung cancers has not been fully established yet." (PMID 36209201, 2022). "Therefore, we confirmed that PLEKHH2 promotes the activity of the PI3K/AKT signaling pathway by promoting FAK phosphorylation, which then confers a malignant phenotype in lung cancer cells." (PMID 36209201, 2022). "First, we aimed to clarify whether PLEKHH2 expression plays an important role in regulating both the PI3K/AKT and Ras/ERK pathways and promoting the malignant phenotype of lung cancer." (PMID 36209201, 2022). "To further explore the role of the PI3K/AKT signaling pathway in PLEKHH2- mediated regulation of the proliferation and invasion of lung cancer cells, we used a PI3K/AKT pathway inhibitor (LY294002) to inhibit the activity of the PI3K/AKT signaling pathway and upregulate the expression of PLEKHH2." (PMID 36209201, 2022). "Whether PLEKHH2 also binds to these proteins through its FERM domain and plays other regulatory roles in lung cancer remains unknown and could be a subject of future research." (PMID 36209201, 2022). "However, high expression of ADAMTS8, CD36, DPYSL2, PLEKHH2, STX11, and TCF21 tends to lead to better prognosis, which coincides with the difference in expression of these HUB genes in normal samples and lung cancer samples." (PMID 37409245, 2023).
lung carcinoma (continued). "To further verify our hypothesis, we transfected a PLEKHH2 mutant plasmid lacking the FERM domain into lung cancer cell lines." (PMID 36209201, 2022). "Western blot results showed that after inhibiting the PI3K/AKT signaling pathway, the enhanced expression of PLEKHH2 did not significantly promote the expression of proliferation- and invasion-related proteins and the proliferation and invasion abilities of lung cancer cells." (PMID 36209201, 2022). "The results further showed that PLEKHH2 without the FERM domain has a weakened ability to activate the PI3K/AKT pathway and, in turn, the ability to promote lung cancer cell proliferation and invasion." (PMID 36209201, 2022). "We found that upregulation of PLEKHH2 did not significantly promote the activity of the PI3K/AKT pathway or the proliferation and invasion of lung cancer cell lines." (PMID 36209201, 2022).
schizophrenia (2 papers, 2020 to 2022). A major psychotic disorder characterized by abnormalities in the perception or expression of reality. "Transcriptome analysis of fibroblasts from patients with schizophrenia has revealed differential expression of schizophrenia-related genes, including PLEKHH2." (PMID 36209201, 2022). "The genes HGF, PRRT2, EGR1, EGR3, C11orf87, TLR3 and PLEKHH2 have been reported in either genetic analysis or gene expression analysis of schizophrenia, and were all upregulated in fibroblasts from patients in our study." (PMID 31959813, 2020).
cardioembolic stroke (1 paper, 2019). "CAV1, SURF1, PLEKHH2, ECD, BNIP1, CAV2 are found to be associated with cardioembolic stroke and Small vessel stroke in Europeans." (PMID 32038707, 2019).
coronary artery disease (1 paper, 2023). "PLEKHH2 variants have been associated with diabetes nephropathy, coronary artery disease and venous thromboembolism, and have interacted with antihypertensive drugs for new-onset diabetes." (PMID 36981027, 2023).
non-small cell lung carcinoma (1 paper, 2022). A group of at least three distinct histological types of lung cancer, including non-small cell squamous cell carcinoma, adenocarcinoma, and large cell carcinoma. "We report that PLEKHH2 showed enhanced cytoplasmic expression in non-small cell lung cancer (NSCLC)." (PMID 36209201, 2022).
tumor (2 papers, 2022 to 2026). "Tumors with increased PLEKHH2 expression tended to display more malignant phenotypes such as lower differentiation (P = 0.001), greater clinical tumor size (P = 0.002), higher tumor node metastasis (TNM) stage (P = 0.013), and positive lymphatic metastasis (P = 0.002)." (PMID 36209201, 2022). "Pathological biopsy revealed that the tumor was composed of monomorphic spindle cells arranged in a fascicular growth pattern with extensive necrosis and coexpression of S100 and CD34; subsequently, PLEKHH2::ALK fusion was identified via next-generation sequencing (NGS)." (PMID 41672777, 2026).
adenocarcinoma (1 paper, 2022). A common cancer characterized by the presence of malignant glandular cells. "We transfected a cDNA plasmid of PLEKHH2 into the adenocarcinoma cell lines A549 and H1299." (PMID 36209201, 2022).
cancer (1 paper, 2017). A tumor composed of atypical neoplastic, often pleomorphic cells that invade other tissues. "The role of PLEKHH2, USP47 and THYN1 has not been extensively studied in cancer progression." (PMID 28122328, 2017).
PLEKHH2 also shares sentences with these, for which no sentence is quoted: cholelithiasis (1 paper); diabetes (1); diabetes nephropathy (1); Hypertension (1); small vessel stroke (1); venous thromboembolism (1); viral infections (1).